PRAMEF6 (PRAME family member 6)
Description:
Substrate-recognition component of a Cul2-RING (CRL2) E3 ubiquitin-protein ligase complex, which mediates ubiquitination of target proteins, leading to their degradation. The CRL2(PRAMEF6) complex mediates ubiquitination and degradation of truncated MSRB1/SEPX1 selenoproteins produced by failed UGA/Sec decoding.
Tractability: PROTAC: ubiquitination databases record sites on it.
Gene: Protein-coding gene on chromosome 1 (12,938,472 to 12,947,580, reverse strand). Ensembl gene ENSG00000232423.
Gene Ontology:
Molecular function: ubiquitin-like ligase-substrate adaptor activity
Biological process: proteasome-mediated ubiquitin-dependent protein catabolic process; negative regulation of apoptotic process; negative regulation of cell differentiation; negative regulation of DNA-templated transcription; positive regulation of cell population proliferation; protein ubiquitination
Cellular component: Cul2-RING ubiquitin ligase complex; cytoplasm
Genetic constraint (gnomAD): Loss-of-function variants: 0 observed, 6.07 expected, observed/expected ratio (o/e) 0, 90% interval 0 to 0.49. That is too few expected variants to judge how well the gene tolerates losing a copy. Missense variants: 24 observed, 108.63 expected, observed/expected ratio (o/e) 0.22, 90% interval 0.16 to 0.31. Synonymous variants: 4 observed, 36.37 expected, observed/expected ratio (o/e) 0.11, 90% interval 0.053 to 0.25.
Homologues: Orthologues: mouse Pramel13 (46% identical), rat Pramef12 (45% identical), rat Pramef8 (44% identical), mouse Pramel12 (44% identical), mouse Pramel15 (43% identical), rat Pramef20 (43% identical), rat Pramef20l1 (43% identical), rat Pramef5 (43% identical), rat Pramel36l1 (43% identical), mouse Pramel16 (42% identical), mouse Pramel31 (42% identical), rat LOC120103107 (42% identical), and 78 more. Paralogues in human: PRAMEF5 (99% identical), PRAMEF15 (97% identical), PRAMEF9 (97% identical), PRAMEF27 (97% identical), PRAMEF25 (97% identical), PRAMEF26 (97% identical), PRAMEF4 (96% identical), PRAMEF11 (96% identical), PRAMEF20 (82% identical), PRAMEF12 (63% identical), PRAMEF8 (63% identical), PRAMEF7 (63% identical), and 12 more.